MSMB (microseminoprotein beta)
Diseases named in the same sentence as MSMB in open-access papers (continued):
Sharing a sentence is not in itself a finding about the gene and the disease.
breast carcinoma (2 papers, 2014 to 2025). "CNOT7 and its paralog CNOT8 can influence the stability of cell cycle-related genes MSMB, PMP22, and Cyclin G2 through their deadenylation ability, promoting cell proliferation in breast cancer." (PMID 41249119, 2025).
prostate adenocarcinoma (2 papers, 2010 to 2017). "In prostate adenocarcinoma tissues, however, MSMB expression derived almost completely from MSMB1, which is present at 96% of total MSMB expression." (PMID 20569440, 2010).
psoriasis (2 papers, 2023 to 2025). An autoimmune condition characterized by red, well-delineated plaques with silvery scales that are usually on the extensor surfaces and scalp. "MSMB has been previously shown to be down-regulated in the lesional skin of psoriasis patients compared to non-lesional and healthy skin." (PMID 36901987, 2023).
Azoospermia (1 paper, 2024). Absence of any measurable level of sperm,whereby spermatozoa cannot be observed even after centrifugation of the semen pellet. "Considering that MSMB protein is secreted from the prostate gland and added to semen at the time of ejaculation, genetic variations in this gene apparently cannot affect the spermatogenesis that was previously performed in the testis on the upstream of this pathway, causing azoospermia." (PMID 39205920, 2024). "Based on the results of previous studies, MSMB level was significantly increased in subfertile (oligozoospermia and azoospermia) cases' seminal plasma samples when compared with fertile controls." (PMID 39205920, 2024).
gastric cancer (1 paper, 2018). A primary or metastatic malignant neoplasm involving the stomach. "Among the top 10 DRGs for Chinese (GSE54129), six genes have been reported to be gastric cancer (GC) related (REG4, ANXA13, C7, ASS1, MSMB, CREB1) and the rest four were directly regulated by known gastric cancer genes in our GRNs, in which two genes are also cancer related (BPTF, CLCA1)." (PMID 29745833, 2018).
infertile (1 paper, 2024). "No studies have been found on the genetic variants in the promoter and the coding sequences of interacting domains of the MSMB gene, as well as its expression level in sperm of unexplained infertile men." (PMID 39205920, 2024). "In conclusion, our results illustrated that variations detected in the MSMB gene may not be associated with the IUI success rate in unexplained infertile men." (PMID 39205920, 2024). "The present study aimed to evaluate MSMB gene variations and protein expression on IUI success rate in unexplained infertile men." (PMID 39205920, 2024).
Insulin resistance (1 paper, 2015). Increased resistance towards insulin, that is, diminished effectiveness of insulin in reducing blood glucose levels. "High fasting levels of TG, which is a common component of insulin resistance, are significantly associated with GIP (r = −0.43, n = 18, p = 0.05) and MTRNR2L1 (r = 0.65, n = 18, p < 0.01) but only tend to be associated with MSMB (r = −0.40, n = 18, p = 0.08)." (PMID 26376914, 2015).
pterygium (1 paper, 2009). A wedge-shaped fibrovascular lesion arising from the bulbar conjunctiva and extending to the cornea. "MSMB, on the other hand, was detected prominently in the basal epithelial layer of pterygium, with some staining also in the superficial stromal cells adjacent to the basal epithelia." (PMID 19272163, 2009). "Genes up-regulated in pterygium include fibronectin (FN1), CEACAM5 (CEA), CD24, SPARC, MSMB and TFF1." (PMID 19272163, 2009). "Our results show that protein expression levels for keratin 6, CEACAM5, CD24, MSMB and MUC5AC were increased, whereas NR4A2 and IGFBP3 were reduced in pterygium, consistent with the transcript changes detected by the microarray analysis." (PMID 19272163, 2009). "In pterygium, there was elevation of transcript and protein expression of MUC5AC and MSMB." (PMID 19272163, 2009).
sexually transmitted infections (1 paper, 2019). "MSMB gene polymorphism (rs10993994) has exhibited an association both with PC as well as the susceptibility to sexually transmitted infections." (PMID 30774776, 2019).
signet ring cell carcinoma (1 paper, 2023). A usually aggressive, poorly differentiated invasive adenocarcinoma characterized by the presence of malignant glandular cells in which the nucleus is pressed to one side by the presence of intracytoplasmic mucus. "Microseminoprotein-beta (MSMB) can be used as a marker gene to guide the identification of moderately/poorly differentiated adenocarcinoma and signet ring cell carcinoma (SRCC)." (PMID 37225691, 2023).
tumor (31 papers, 2010 to 2025). "Specifically, SPON2 was enriched in tumor-associated epithelial clusters, while MSMB was detected in secretory/luminal epithelial subsets." (PMID 41200187, 2025). "HNF1B and MSMB also encode multiple isoforms, and differential isoform expression for these genes has been observed in comparisons of tumor and normal prostate tissues." (PMID 29156765, 2017). "We confirm a number of previously published molecular changes associated with high risk disease, including MYC amplification, and NKX3-1, RB1 and PTEN deletions, as well as over-expression of PCA3 and AMACR, and loss of MSMB in tumour tissue." (PMID 26501111, 2015). "Notably, SPON2 expression was enriched in tumor-associated epithelial clusters, while MSMB expression was detected in secretory/luminal epithelial cell subsets." (PMID 41200187, 2025). "It is conceivable that increased expression of NCOA4 is associated with tumor initiation, as reflected by its association with risk in solely normal tissue, while decreased expression of MSMB is associated with both tumor initiation and maintenance or progression." (PMID 21085629, 2010). "In tumor tissue, MSMB retains its association with risk allele status (p-value range, 0.016–0.053)." (PMID 21085629, 2010). "Tumor microenvironment analysis showed that a high proportion of MSMB/Macrophage was significantly correlated with a lower stromal component, which was closely associated with tumor progression, which may imply that a high proportion of MSMB/Macrophage is associated with a better prognosis." (PMID 40002900, 2025). "The IHC results revealed that ARHGEF38 protein was highly expressed in tumor tissues, while MSMB exhibited reduced expression in tumor tissues compared to para-cancerous tissues." (PMID 40260298, 2025). "A bar plot illustrates the relative expression levels of SPON2 and MSMB in tumor versus normal samples, highlighting SPON2 as the most strongly upregulated marker in this cohort." (PMID 41200187, 2025). "MSMB also demonstrated upregulation in tumor samples, with a mean ΔΔCt of –1.4, indicating a ~2.6-fold increase (mean fold-change = 2.6 ± 0.5, mean ± SD) in expression." (PMID 41200187, 2025). "IHC results confirmed that ARHGEF38 protein was highly expressed in tumor tissues, while MSMB expression was markedly reduced." (PMID 40260298, 2025). "The IHC results confirmed that ARHGEF38 protein was highly expressed in tumor tissues, while MSMB expression was markedly reduced, consistent with the qRT-PCR and Western blot data." (PMID 40260298, 2025). "Observations of higher MSMB expression in benign prostate tissue prompted some investigators to suggest that MSMB has a tumor suppressive role in PC." (PMID 26939004, 2016). "When the tumour samples were stratified into low (6 and 7) and high (8 and 9) sum Gleason scores urinary MSMB demonstrated high levels of specificity and sensitivity particularly when compared to urinary PSA." (PMID 20967219, 2010). "The qRT-PCR validation of our findings confirms our microarray observations and found that SPON2 had high expression (approximately 18-fold increase) and MSMB had a moderate overexpression (approximately 2.6-fold increase) in tumor tissues compared to the adjacent normal tissues." (PMID 41200187, 2025). "In particular, converging evidence from population genetic and tumour sequencing analyses implicates MSMB as having an important protective role in prostate tumourigenesis, both in European and African-ancestry men, which is particularly marked for aggressive and early onset disease." (PMID 38878676, 2024). "Functional studies in vivo and in vitro also suggest a tumor suppressive role for MSMB." (PMID 26939004, 2016). "Subsequently, in reporting that MSMB gene expression is significantly depleted among high grade tumour when compared to expression in benign cells, we reiterate, through an independent line of evidence, that this gene may be particularly relevant to tumourigenesis and risk for aggressive disease." (PMID 38878676, 2024).
tumor (continued). "Notably, associations between rs10993994 genotype and expression of MSMB and NCOA4 are observed in histologically normal prostate tissue, whereas in tumor tissue an association is detected with only MSMB (albeit at an attenuated level relative to the normal tissue)." (PMID 21085629, 2010). "MSMB (microseminoprotein-beta) is a prostate-secreted protein that has been investigated to shed light on it being a possible PSA alternative and tumor suppressor, where it frequently shows lower expression in higher stages of cancer." (PMID 41200187, 2025). "Normality of ΔΔCt values was assessed using the Shapiro–Wilk test (p > 0.05 for both genes); paired two-tailed t-tests were then applied to compare tumor versus matched normal tissues, yielding p = 0.003 for SPON2 and p = 0.02 for MSMB." (PMID 41200187, 2025). "Subcluster 5, distinctly derived from the tumour tissue, overexpressed mucus secretion‐related genes (CXCL17, TFF3, MUC5AC, SPINK4 and MSMB, etc.)." (PMID 35075805, 2022). "AR can modulate the expression of TFs, biomarkers and vital tumour promoters in PrCa development, such as KLK2, KLK3, MYC, MSMB and TMPRSS2." (PMID 32397189, 2020). "Expression levels of MSMB and NCOA4 transcripts were significantly higher in normal compared with tumor tissue (p<0.0001), consistent with previously published reports." (PMID 21085629, 2010). "Our results revealed that, compared to para-cancerous tissues, the expression levels of SLC14A1, NEFH, MSMB, KRT23, and KRT15 were significantly downregulated in PCa tumor tissues, while ARHGEF38 expression was notably upregulated, consistent with our initial predictions." (PMID 40260298, 2025). "Each isoform of MSMB and NCOA4 was expressed in both normal and tumor prostatic tissue." (PMID 21085629, 2010). "Consistent with the association in prostate tissue there was a significant decrease in urinary MSMB in men with tumours compared with men with no history of prostate disease (Supporting Document 4A) (p<0.0001)." (PMID 20967219, 2010). "Though this study demonstrated preliminary serum reactivity of synthetic SPON2 and MSMB epitopes by ELISA, we did not perform quantitative protein-level validation using standard ELISA kits or immunoblotting, nor did we conduct immunohistochemistry (IHC) on tumor tissues." (PMID 41200187, 2025). "We used immunohistochemistry to quantify the MSMB protein (PSP-94) expression in morphologically normal and tumor tissues from patients with and without 5-year distant metastasis." (PMID 41317378, 2025).
cancer (28 papers, 2009 to 2025). A tumor composed of atypical neoplastic, often pleomorphic cells that invade other tissues. "Some of the genes were related to animal disease, such as the immunoglobulin binding factor MSMB (β-microseminoprotein), genes encoding the membrane attack complex/perforin protein, as well as cancer related gene headcase and ARSB (arylsulfatase B)." (PMID 27782082, 2016). "In contrast, there was a very strong association between low MSMB levels in serum and TT risk genotype of the SNP rs10993994 of both cancer cases and controls (p<0.0001; 0.0001, respectively)." (PMID 26939004, 2016). "This SNP is located in 10q11, near the MSMB gene and the effects of the identified allele (T) have been shown to decrease its expression levels, thus decreasing its cancer suppressor function." (PMID 22046276, 2011). "In addition, in 19 cancer cell lines of various tissue types expressing MSMB, those carrying the TT genotype have decreased MSMB expression relative to those carrying a C allele." (PMID 21085629, 2010). "The results showed that the proportion of high MSMB expression in MSMB/Epithelial_cells progressively decreased with cancer progression." (PMID 40002900, 2025). "Using spatial transcriptomics data, we identified MSMB as the genome-wide top-most predictive gene to distinguish benign regions from high grade cancer regions that comparatively had five-fold lower MSMB expression." (PMID 38878676, 2024). "The Cancer Mutations track contains four reported mutations for MSMB (MSMB:ENST00000358559), indicative of the involvement of this gene in cancer, but all of them within the gene's exons." (PMID 22046276, 2011). "The MSMB protein is underexpressed in PrCa and it was previously proposed to be an independent marker for the recurrence of cancer after radical prostatectomy." (PMID 19997100, 2010). "As can be inferred from the array signal intensity levels, expression of the major functional prostatic secretory proteins ACPP, AZGP1, KLK2, KLK3, and MSMB was down-regulated in the cancer cells compared to the luminal cells." (PMID 20021671, 2009). "The downregulated genes that we have identified in NPC, such as MSMB, UPK1B, and FOXJ1, may be associated with the development or progression of NPC and may play different roles from their roles in other cancers." (PMID 33564686, 2021). "We did not found a significant difference in serum MSMB levels between the cancer cases and the controls when the comparison was performed without adjustment with age and free or total PSA." (PMID 26939004, 2016). "Unlike KLK3 and ACPP, luminal expression of MSMB appears not to be regulated by stromal influence, and is known to be down-regulated in cancer cells." (PMID 20021671, 2009). "In addition, MSMB was highly expressed in clusters foveolar cells-1 and -2 but was almost absent in cancer cell-containing clusters and intestinal metaplasia cells." (PMID 40925382, 2025). "We did not identify any correlations of total gene expression with cancer status for the JAZF1, MSMB, HNF1B, MYEOV or CTBP2 genes." (PMID 20569440, 2010). "Urinary MSMB concentrations were determined by ELISA and correlated with urinary PSA, the presence or absence of cancer, rs10993994 genotype and age of onset." (PMID 20967219, 2010).
adenocarcinoma (1 paper, 2023). A common cancer characterized by the presence of malignant glandular cells. "The SRCC cell line NUGC4 exhibited a higher expression level of MSMB than the poorly differentiated MKN-45 adenocarcinoma cell line." (PMID 37225691, 2023).
MSMB also shares sentences with these, for which no sentence is quoted: prion disease (15 papers); neuroblastoma (5); lung carcinoma (4); fungal infection (3); infection (3); scrapie (3); prostate (2); acute lymphoblastic leukemia (1); animal disease (1); Cachexia (1); chronic prostatitis (1); diabetes (1); dyslipidemia (1); hepatocellular carcinoma (1); hereditary prostate cancer (1); inflammatory bowel disease (1); metastatic disease (1); neurodegenerative disease (1); neurological disease (1); Obesity (1); ovarian carcinoma (1); proteinopathy (1); sleep disorder (1); thyroid dyshormonogenesis (1).